BRCA2 (BRCA2 DNA repair associated)
Diseases named in the same sentence as BRCA2 in open-access papers (continued):
Sharing a sentence is not in itself a finding about the gene and the disease.
breast cancer (continued). "Studies by the Consortium of Investigators of Modifiers of BRCA1/2 (CIMBA) have demonstrated that common alleles in RAD51, FGFR2, MAP3K1, TOX3/TNRC9, LSP1, SLC4A7/NEK10, a 2q35 locus and a 5p12 locus affect breast cancer risk in BRCA2 mutation carriers." (PMID 22513257, 2012). "Expression of the breast cancer susceptibility gene, BRCA2, was most strongly correlated with gene sets representing cell cycle checkpoints and DNA damage response." (PMID 22824328, 2012). "BRCA1 and BRCA2 mutations were also identified in 15.4% for bilateral breast cancer and in 17.9% for multiple organ cancer, and BRCA2 mutations were identified in 25% for male breast cancer in one study." (PMID 22382806, 2012). "This revealed that each copy of the higher-expression haplotype 4 was associated with a reduced risk of breast cancer for BRCA2 mutation carriers (HR = 0.84, 95%CI: 0.73 to 0.97, P = 0.014)." (PMID 22513257, 2012). "This is perhaps the clearest evidence so far of a departure from a multiplicative interaction between a common susceptibility locus and a BRCA2 mutation on the risk of developing breast cancer." (PMID 22348646, 2012). "Consistent with this notion, we previously showed that loss of heterozygosity, which is one of the mechanisms of BRCA2 inactivation, was present in a mammary tumor." (PMID 22471976, 2012). "Approximately 10 % of men with breast cancer are known to have a genetic predisposition, and especially BRCA2 mutations seem to be important." (PMID 22527098, 2012). "This is significantly lower than for carriers of a pathogenic mutation in BRCA1 or BRCA2, who display a life-time risk for breast cancer of ~60–80%." (PMID 22672556, 2012). "Mutations in the breast cancer susceptibility gene, BRCA2, have been found in most cases of inherited human breast cancer." (PMID 23071527, 2012). "A different SNP (rs16917302) in ZNF365, which is only weakly correlated with rs10995190 (pairwise r2 is approximately 0.10 in the present sample) was previously identified via a GWAS of breast cancer in BRCA2 mutation carriers." (PMID 22348646, 2012). "The effect of the expression haplotypes on breast cancer risk in BRCA2 mutation carriers was investigated in 2,754 carriers." (PMID 22513257, 2012). "These loci account for approximately 4% of the genetic variation observed in the penetrance of BRCA2 mutations in breast cancer." (PMID 22513257, 2012). "Previous studies found that mammographic density modifies breast cancer risk for BRCA2 mutation carriers, raising the possibility that this locus modifies breast cancer risk for BRCA2 mutation carriers through its influence on mammographic density." (PMID 22348646, 2012). "This excludes highly penetrant mutations with well-characterized inheritance patterns, such as BRCA1/BRCA2 mutations in breast cancer." (PMID 23071447, 2012). "The goal of the current study was to evaluate the relationship between breastfeeding and breast cancer risk among women with a BRCA1 or BRCA2 mutation." (PMID 22405187, 2012). "Although the mean age of breast cancer diagnosis of BRCA2 mutation carriers (mean age 45.7) are slightly higher than that of BRCA1 mutation carriers (mean age 40.4), the difference was not significant (p = 0.455, Wilcoxon test)." (PMID 22970155, 2012). "Women carrying a deleterious BRCA1 or BRCA2 mutation not only face a strongly elevated lifetime risk for the development of breast and ovarian cancer but also for a second breast cancer." (PMID 23216834, 2012). "Mutations in BRCA1 and BRCA2 confer a high risk of breast cancer (BC), but the magnitude of this risk seems to vary according to the study and various factors." (PMID 22762150, 2012).
breast cancer (continued). "A recent study involving single nucleotide polymorphism analysis of intronic markers suggested that the canine BRCA2 gene locus is associated with mammary tumors." (PMID 23071527, 2012). "Consistent with this notion, we have previously demonstrated that loss of heterozygosity, which is one of the mechanisms of BRCA2 inactivation, in mammary tumors." (PMID 23071527, 2012). "The genes BRCA1 and BRCA2 are associated with the risk of breast cancer, however these genes account for only 30-40% of the familial breast cancer cases, and only 3-4% of the total number of breast cancer cases." (PMID 22867275, 2012). "Further studies with larger population-based datasets are needed to determine the prevalence of BRCA1 and BRCA2 mutations and the cost-effectiveness of testing women diagnosed with isolated breast cancer, aged 40 to 49 years old." (PMID 23116406, 2012). "The identification of BRCA1 and BRCA2 mutations has dramatically changed the landscape of breast cancer in the past decade." (PMID 22290208, 2012). "Germline mutations in one allele of the BRCA2 tumor-suppressor gene confer greatly increased risk of developing breast cancer." (PMID 21958427, 2011). "Capan-1 is a particularly intriguing cell line as it is both BRCA2 deficient, like many familial breast cancers, yet derived from a pancreatic adenocarcinoma." (PMID 21750719, 2011). "The BRCA1 and BRCA2 tumor suppressor genes have been established as important high penetrance familial breast cancer susceptibility alleles." (PMID 21835029, 2011). "Although there have been several studies that estimate the risk of contralateral breast cancer in women with a BRCA1 or BRCA2 mutation, there has been little research on the predictors of contralateral breast cancer risk." (PMID 21487411, 2011). "It is clear that the genomes of BRCA2 mutated breast cancers classified as diploid are extensively altered, and individual examples are presented here to demonstrate complex patterns of genomic changes." (PMID 21958427, 2011). "The study included three studies that examined the breast cancer risk reduction in BRCA2 carriers specifically." (PMID 21487411, 2011). "SNP rs10941679 at 5p12 was also associated with a higher risk of PR-positive breast cancer for BRCA2 mutation carriers (per-allele HR for PR-positive = 1.15." (PMID 22053997, 2011). "We have recently reported that a family history of cancer influences breast cancer risk in women with a BRCA1 or BRCA2 mutation." (PMID 21487411, 2011). "Some risk is conferred by rare variants with large effects, such as the BRCA1/BRCA2 mutations that increase breast cancer susceptibility." (PMID 21244661, 2011). "For example, three AFAS probes designed to detect the transcripts encoded in the antisense strand of BRCA2 (breast cancer 2, early onset, U43746) revealed altered expression balances for the sense-AFAS transcripts originating from this gene." (PMID 21575255, 2011). "Currently known susceptibility genes such as BRCA1 and BRCA2 explain less than 25% of familial aggregation of breast cancer, which suggests the involvement of additional susceptibility genes." (PMID 21774837, 2011). "Using this cohort, we estimate the contralateral breast cancer risks in women with a BRCA1 or BRCA2 mutation, and we measure the extent to which host factors, family history, and cancer treatments modify the risk." (PMID 21487411, 2011). "BRCA2-deficient mammary tumors growing in genetically engineered mice demonstrated high sensitivity to olaparib and carboplatin." (PMID 21819606, 2011). "This study is evaluating the behavioral and psychosocial effects of the routine offer of RGCT to newly diagnosed primary breast cancer patients who meet criteria for being at-risk of having a BRCA1 or BRCA2 gene mutation." (PMID 21219598, 2011). "Histopathological data, when available, showed grade II or III, oestrogen-receptor (ER) positive and HER2-negative breast tumours, a phenotype consistent with BRCA2-associated breast cancers." (PMID 21939546, 2011).
breast cancer (continued). "Thirty-three female breast cancer patients carrying the same 999del5 BRCA2 germline mutation constituted the study group analyzed with array CGH (comparative genomic hybridization)." (PMID 21958427, 2011). "PALB2, like BRCA2, is a breast cancer suppressor and is also associated with Fanconi anemia, a developmental and tumor predisposition syndrome." (PMID 22194698, 2011). "A number of studies examining the incidence of breast cancer have reported a lower likelihood amongst BRCA2-mutation carriers compared to BRCA1-mutation carriers." (PMID 22312502, 2011). "Invasive ductal carcinoma, NOS (not otherwise specified) type, is the most common histologic form of all hereditary breast cancers, including BRCA1- and BRCA2-associated breast cancers." (PMID 22295226, 2011). "We performed mutation analysis of BRCA1 and BRCA2 on 127 unselected patients with breast cancer in Athens, Greece." (PMID 22085629, 2011). "Current estimates indicate that women who carry mutations in the BRCA1 or BRCA2 genes have up to an 85% lifetime risk of developing breast cancer, and can also have up to a 60% lifetime risk of developing ovarian cancer." (PMID 21219598, 2011). "MAP3K1 and SLC4A7/NEK10 were associated only with risk of PR-positive breast cancer among BRCA2 mutation carriers." (PMID 22053997, 2011). "The mutations detected in male breast cancer were c.7806-2A > G and c.3975_3978dupTGCT in BRCA2 gene." (PMID 21232165, 2011). "In these British and American studies, between one-half and two-thirds of the breast cancer patients carrying a BRCA1 or BRCA2 mutation opted for a bilateral mastectomy, with some opting for a delayed CPM instead of direct BLM." (PMID 21219598, 2011). "Inheritance of a mutation in either BRCA1 or BRCA2 accounts for approximately 5% of all breast cancer cases, but varies by country." (PMID 22085629, 2011). "While BRCA1 and BRCA2 mutations are highly penetrant, resulting in higher risk for breast cancer, both of these genes are also highly polymorphic." (PMID 21708019, 2011). "It has been reported that only 5.5% of women with a BRCA1 or BRCA2 mutation have used tamoxifen to reduce their breast cancer risk." (PMID 22312502, 2011). "Although high-penetrant susceptibility genes such as BRCA1 and BRCA2 demonstrate potent associations with the familiar breast cancer, many low-penetrant susceptibility genes predisposing to breast cancer remain to be elucidated." (PMID 21917182, 2011). "An association was observed between p.Arg280His-rs25489 and breast cancer risk for BRCA2 mutation carriers, with rare homozygotes at increased risk relative to common homozygotes (hazard ratio: 22.3, 95% confidence interval: 14.3–34, P<0.001)." (PMID 21427728, 2011). "It has however been shown that approximately 10% of men with breast cancer carry BRCA2 mutations, while mutations in BRCA1 are exceedingly rare." (PMID 21949660, 2011). "FANCD1 has been identified as the breast cancer susceptibility protein BRCA2 which regulates RAD51 in homologous recombination repair (HRR)." (PMID 21573016, 2011). "Women who carry a germline mutation in either the BRCA1 or the BRCA2 gene face a high lifetime risk of breast cancer and, once diagnosed with breast cancer, face a high risk of second primary cancer in the contralateral breast." (PMID 21487411, 2011). "Ten distinct types of BRCA2 variants were detected by these researchers, 9 in exon 11, and only one in exon 22, the 9140delA mutation in a Muhajir breast cancer patient." (PMID 21559243, 2011). "BRCA1 and BRCA2, like other genes, have not only served as molecular markers for hereditary breast cancer risk screening but also become important indicators for breast cancer prevention, treatment, and prognosis." (PMID 21559243, 2011). "Families are being tested for mutations in BRCA1, BRCA2 and the other major breast cancer susceptibility genes." (PMID 21352566, 2011).
breast cancer (continued). "Mutations in BRCA1 (and BRCA2) confer a high risk for breast cancer, with a lifetime risk of up to 80%." (PMID 22032724, 2011). "In conclusion, our results demonstrate phenotypic heterogeneity of breast cancers arising in carriers of the same 999del5 BRCA2 mutation." (PMID 21958427, 2011). "Results from the CIMBA study suggested an increased risk of breast cancer for BRCA2 mutation carriers with two copies of the ‘C’ allele at the 135G → C SNP (rs 1801320) in the 5′ untranslated region of RAD51." (PMID 21427728, 2011). "The contribution of BRCA2 mutation to the breast cancer FRR was estimated to be 8.4% for relatives of both ER-positive and ER-negative patients." (PMID 20146796, 2010). "The occurrence of clinically important mutations in BRCA2 in familial cases of breast cancer was 2 of the 16 individuals analyzed (12.5%)." (PMID 20380699, 2010). "BRCA1 and BRCA2 mutation carriers are at increased risk for developing breast cancer and/or ovarian cancer." (PMID 21114847, 2010). "Our study was performed to identify germline mutations in some exons of BRCA1 and BRCA2 genes for the early detection of presymptomatic breast cancer in females." (PMID 20579331, 2010). "Although inherited mutations in a small number of genes account for only about five to ten percent of women's cancers, by far the BRCA1 and BRCA2 gene mutations are the most common examples of this observation (50–70% of familial breast cancers)." (PMID 20111735, 2010). "There have been several case control studies seeking BRCA1 and BRCA2 variants associated with an increased risk of breast cancer." (PMID 20807450, 2010). "Studies on large series of BRCA2-associated breast cancers indicate that these tumours are predominantly high-grade IDCs of no special marker subtype, and that they are more often oestrogen- and progesterone-receptor positive." (PMID 20877358, 2010). "The BRCAPRO model calculates risk of developing breast cancer based on the probability of carrying a BRCA1 or BRCA2 mutation." (PMID 21037853, 2010). "In this work, we analyzed and compared aCGH data from a large series of mouse and human BRCA1- and BRCA2-mutated breast cancers, in order to obtain a complete collection of genes and loci that are recurrently gained or lost in tumors of both species." (PMID 20735817, 2010). "Bilateral prophylactic mastectomy has been found to reduce the risk of a future breast cancer for a woman carrying a BRCA1 or BRCA2 mutation by as much as 90%." (PMID 20180951, 2010). "In some populations BRCA1 and BRCA2 mutations can account for ten percent of all breast cancers (Ashkenazi Jewish populations) and ovarian cancers but in many ethnic groups and in all populations taken together these mutations are much rarer." (PMID 20111735, 2010). "Of the 3,659 cases and 4,897 controls in phase 1 of that study, imputation revealed that the locus identified in our BRCA2 study, rs16917302, was significantly associated with risk for breast cancer (p = 0.02) (Easton DF, personal communication)." (PMID 21060860, 2010). "Meanwhile, loss or reduction of BRCA1 and BRCA2 expression has been exhibited in sporadic breast cancers." (PMID 20230646, 2010). "For counseling of women identified as having a double heterozygote for mutations in BRCA1 and BRCA2, the risk of transmitting a breast cancer susceptibility gene to any daughters is 3⁄4." (PMID 20579331, 2010). "Previously identified breast cancer susceptibility loci had the most significant associations among BRCA2 mutation carriers (FGFR2: per allele and TOX3: per allele )." (PMID 21060860, 2010).
breast cancer (continued). "BRCA1 and BRCA2 mutations together were estimated to explain 32% of breast cancer FRR for ER-negative disease and 9.4% of FRR for ER-positive disease." (PMID 20146796, 2010). "Instead, we estimated the contribution of BRCA1 and BRCA2 mutations to the breast cancer FRR by tumour subtype by modeling their effects in the risk prediction algorithm BOADICEA." (PMID 20146796, 2010). "Only a small proportion of breast cancer cases can be attributed to mutations in high-penetrance genes such as BRCA1 or BRCA2, and much of the remaining cases are attributed to more common gene variants with lower penetrance." (PMID 21108795, 2010). "Similar trends are also observed in BRCA2 carriers, as the risk ranges between 33% and 95% for breast cancer, and between 4% and 47% for ovarian cancer." (PMID 20961453, 2010). "The breast cancer susceptibility gene BRCA2 (OMIM#600185) is also related to an increased risk of ovarian cancer." (PMID 20380699, 2010). "Among mutations in the BRCA2 gene, one c.6631delTTAAATG mutation carrier had a sister with breast cancer, her aunt had ovarian cancer, and in addition, her brother had prostate cancer and her uncle had gastric cancer." (PMID 20380699, 2010). "If replicated, the two additional SNPs identified here would only explain about 1.7% of the variance in breast cancer risk among BRCA2 mutation carriers." (PMID 21060860, 2010). "Germline BRCA2 mutations in female carriers confer a cumulative breast cancer risk at age 70 years of 49% (95% CI: 40–57%), an ovarian cancer risk of 18% (95% CI: 13–23%), and a moderate increased risk of pancreatic cancer." (PMID 20877358, 2010). "The Breast Cancer Linkage Consortium found a significant relative risk of 4.65 for prostate cancer in male carriers of a deleterious BRCA2 mutation that rose to 7.33 in men under 65 years of age." (PMID 20585617, 2010). "To date, only one BRCA2-mutated breast cancer xenografts (MX1) is available, but its characterisation has not been described in detail." (PMID 20877358, 2010). "The human breast cancer susceptibility gene BRCA2 encodes a protein widely studied due to its importance in DNA repair." (PMID 20543987, 2010). "BRCA1- and BRCA2-mutated breast cancers are associated with increased amounts of chromosomal aberrations, presumably due their functions in genome repair." (PMID 20735817, 2010). "Freedman at al. investigated if common BRCA2 variants contribute to the more common forms of breast cancer in a large multiethnic cohort." (PMID 20807450, 2010). "Here, we report the establishment and characterisation of a novel xenograft, human breast cancer xenograft (HBCx-17) established from a breast cancer in a woman carrying a BRCA2 germline mutation." (PMID 20877358, 2010). "In contrast, the shape of the overall breast cancer incidence curve in BRCA2 mutation carriers is similar to that for ER-positive disease, where incidence increases with age, with an inflexion at about age 50 years." (PMID 20482762, 2010). "These include Rad52, the human Rad51 paralogs Rad51B, Rad51C, Rad51D, Xrcc2, and Xrcc3, and breast cancer susceptibility gene Brca2." (PMID 21129202, 2010). "Several models have been developed for predicting risk of carrying BRCA1 or BRCA2 mutation and subsequently developing breast cancer." (PMID 20482762, 2010). "The most significant association was observed for FGFR2 rs2981582, a variant previously shown to be associated with increased risk of BRCA2-related breast cancer." (PMID 21060860, 2010). "Over 2,000 unique BRCA1 and BRCA2 missense variants have been identified, located throughout the whole gene (Breast Cancer Information Core Database (BIC database))." (PMID 24281179, 2010).